BRCA2 (BRCA2 DNA repair associated)
Diseases named in the same sentence as BRCA2 in open-access papers (continued):
Sharing a sentence is not in itself a finding about the gene and the disease.
Fanconi anemia (continued). "Interestingly, the gene underlying the D1 subtype of Fanconi anemia, FANCD1, was found to be BRCA2 and biallelic mutations in BRCA2/FANCD1 originate a phenotype with high risk of childhood malignancies, very similar to that produced by PALB2/FANCN biallelic mutations." (PMID 23935836, 2013). "After discovering that it was associated with Fanconi anemia, they screened for mutations in RAD51C in 1100 hereditary breast (HBC) and HBOC families, hypothesizing that it would be similar to BRIP1 and BRCA2 in which biallelic mutations cause Fanconi anemia and monoallelic mutations cause HBOC." (PMID 21980511, 2011). "Of these, 16 (48.5%) had DNA-repair deficiencies (DNA-RD), including eight with Fanconi anemia, six with NHEJ1 variants, and two with BRCA2 mutations." (PMID 40047910, 2025). "This variant, found in BRCA2, causes a 93 amino-acid deletion including the RAD51 binding domain, important in the Fanconi Anaemia Pathway for double-strand DNA repair, and is distinct from the highly penetrant familial BRCA mutations." (PMID 41038832, 2025). "Firstly, 2 of the 3 tumors with elevated signature 3 each had 2 pathogenic germline variants both in HR and Fanconi anemia genes (BRCA2/FANCE, BRCA2/FANCD2)." (PMID 40072012, 2025). "Additional genes such as Fanconi Anemia (FA) genes were of interest for this study as identification of the FANCD1 gene as BRCA2 provided the first direct link between FA proteins and DNA repair." (PMID 39085400, 2024). "Fanconi Anemia is, in fact, related to different DNA repair gene mutations, known as FANC genes, with FANCS and FANCD1 corresponding, respectively, to BRCA1 and BRCA2." (PMID 38792636, 2024). "In CRC, significant associations of HR (BRCA1, BRCA2, BARD1, PALB2 and BRIP1) and Fanconi anaemia (FANCA, FANCC and FANCG) genes with TMB were identified." (PMID 37821580, 2023). "As a novel determinant of NDD, OFP was proposed to be distinct from the canonical, BRCA2-and Fanconi Anemia pathway-dependent fork protection (FP) pathway." (PMID 36710880, 2022). "On average, samples with somatic mutations in BRCA1, BRCA2, PTEN, or somatic mutations or gene deletions in any gene belonging to the Fanconi Anemia (FA) or HR pathways showed high ovaHRDscar levels." (PMID 36581696, 2022). "BRCA1 and BRCA2 are part of the BRCA–Fanconi anemia pathway, and other Fanconi genes, such as BRIP1 and RAD51C, have also been associated with an inherited risk of OC." (PMID 36555431, 2022). "Protein interaction analysis indicates that this “genic signature” (Dclre1a, Rev1, Xpa, Pms2, Brca2, Parp2, Smc3, Nbn, Bax) is mainly involved in the Fanconi anemia pathway and homologous recombination repair." (PMID 34573315, 2021). "The study revealed a high rate of inherited variants in patients of young ages with a wide spectrum of variants along the Fanconi anemia pathway (BRCA1, BRCA2, and PALB2)." (PMID 33646313, 2021). "Fanconi anemia genes such as BRCA2/FANCD1, RAD51C and RAD51, homologous to the bacterial RecA, are involved in repair of DNA DSBs by homologous recombination." (PMID 33987182, 2021). "Previous studies showed that DDR genes, including BRCA1, BRCA2, and multiple Fanconi anemia genes, were particularly sensitive to aberrant intronic polyadenylation events." (PMID 34330913, 2021). "Overall, 14.6% had mutations in BRCA1 or BRCA2, 3.3% had mutations in other BRCA–Fanconi anemia genes (BRIP1, PALB2, RAD51C, RAD51D, BARD1), and 0.4% had mutations in mismatch repair genes linked to Lynch syndrome." (PMID 32679669, 2020). "FANCM is part of the Fanconi anemia group together with BRCA2, BRIP1 and PALB2 (also known as FANCD1, FANCJ, and FANCN)." (PMID 33086730, 2020).
Fanconi anemia (continued). "MCM8-9 dimer also works downstream of the Fanconi anemia and the BRCA2/Rad51 pathways and is required for HR that promotes sister chromatid exchanges, as a hexameric ATPase/helicase." (PMID 32841224, 2020). "ClinVar has 18 reports of BRCA2 p.N991D, including familial breast and breast-ovarian cancer, Fanconi anemia, and HBOC syndrome." (PMID 31346352, 2019). "Consistent with both GSEA and the Metascape pathway analyses, we validated downregulation of genes involved in the Fanconi anemia pathway, such as BRCA2 and RAD51, after TIGAR KD with two different shRNAs." (PMID 31508509, 2019). "Several presumably somatic variants were found in DNA repair genes which share homologous DNA repair function with BRCA1 and BRCA2 and are in the same Fanconi anemia pathway." (PMID 31346352, 2019). "Both BRCA1 (FANCS) and BRCA2 (FANCD1) are part of the Fanconi Anemia (FA) mediated DSB repair pathway." (PMID 31225499, 2019). "qRT-PCR data confirmed that the expression of Fanconi anemia-associated genes including BRCA1, BRCA2, PALB2, and RAD51 and cancer-associated genes (ALDH1A3 and IGF1R) was strongly inhibited by FR treatment, as shown by microarray analysis." (PMID 30719229, 2019). "Microarray analysis and real-time quantitative PCR demonstrated downregulation of genes associated with Fanconi anemia (BRCA1 and BRCA2) and 28 driver oncogenes." (PMID 30719229, 2019). "We first sequenced a medulloblastoma from a patient with Fanconi anemia due to compound heterozygosity in BRCA2 (c.657_658delTG and c.7558C>T)." (PMID 30420702, 2018). "This protection of forks from degradation required Rad51 filament formation plus filament stabilization by BRCA2 and the core Fanconi anaemia pathway." (PMID 30220600, 2018). "WES revealed that HMCLs displayed frequent mutations in Fanconi anemia genes (PALB2 [12%], FANCI [12%], FANCA [9%], FANCD2 [9%], BRCA2 [9%]) as well as in helicases (such as RECQL4, 15%, and BLM, 15%) and epigenetic modifiers (e.g., TET2, 15% and SETD2, 6%)." (PMID 30545397, 2018). "In support of this, R-loops accumulate in cells depleted of the BRCA1, BRCA2 or the Fanconi anemia (FA) DNA repair factors, indicating that they play an active role in R-loop dissolution." (PMID 28653981, 2017). "The discovery of BRCA1 and BRCA2 in mitigating R-loop-induced DNA damage was followed by further investigation on the role of the Fanconi anemia (FA) pathway in R-loop resolution." (PMID 28098815, 2017). "BRCA2 is known to function both at sites of DNA double-strand breaks to recruit Rad51 onto ssDNA and at replication forks under stress in the Fanconi anemia pathway." (PMID 28098815, 2017). "Human BRCA2−/− patients develop Fanconi Anaemia, which is characterised by genomic instability and sensitivity to MMC11." (PMID 29184099, 2017). "PALB2 (Partner and Localizer of Breast Cancer 2 (BRCA2)) plays an important role in maintaining genome integrity through its role in the Fanconi anemia (FA) and homologous recombination (HR) DNA repair pathways." (PMID 28858227, 2017). "Defects in major tumor suppressor genes BRCA1 and BRCA2, and a subset of the Fanconi Anemia genes have been shown to result in deregulation in fork remodeling, and most prominently, loss of kilobases of nascent DNA from stalled replication forks." (PMID 29355244, 2017). "As BRCA2 also protects stalled replication forks and is the FANCD1 member of the Fanconi Anemia (FA) pathway, we studied the role of this pathway in preventing R loop accumulation and R loop-dependent genome instability." (PMID 26584049, 2015). "BRCA1 is critically involved with the Fanconi anemia proteins in repairing DNA damage, whereas BRCA2 is itself a Fanconi anemia protein." (PMID 26528434, 2015). "As BRCA2 also protects stalled replication forks and is the FANCD1 member of the Fanconi Anemia (FA) pathway, we investigated the FA role in R loop-dependent genome instability." (PMID 26584049, 2015).
Fanconi anemia (continued). "BRCA2 and other Fanconi Anemia-pathway defective cells are felt to be sensitive to single-agent PARP inhibition and restoring functional BRCA abrogates this activity." (PMID 24624093, 2014). "At stalled replication forks in human cells, DNA-end processing or end protection by Mre11 depends on protein partners, including breast cancer type 2 susceptibility protein (BRCA2) and Fanconi anemia (FA) proteins BRCA1 and FANCD1." (PMID 24062528, 2013). "The BRCA/FA pathway is a key part of the homologous recombination DNA repair machinery and includes the BRCA1 and BRCA2 genes as well as members of the Fanconi anaemia complementation group." (PMID 23587053, 2013). "Recently, the Fanconi anemia/BRCA2 (FA) pathway and Homologous Recombination (HR), a DNA double strand break (DSB) repair mechanism of perfect repair, has been attributed the role as a coordinator of this cascade." (PMID 22905093, 2012). "BRCA1 and BRCA2 gene products are placed within a sequence encompassing the MRE11, Rad50 and NBS1 complex (MRN complex), ATM, CHEK2, BRCA1, BRCA2, and Fanconi anemia proteins." (PMID 17683622, 2007). "In fact, loss of most genes involved in DNA damage checkpoints or DNA damage repair, such as ATM, ATR, BRCA1, BRCA2, Fanconi anemia genes, lead to increased sensitivity to genotoxic agents." (PMID 15494723, 2004). "Notably, BRCA1 (FANCS) and BRCA2 (FANCD1) belong to the Fanconi anemia complementation group, which preserves genomic integrity by repairing DNA interstrand crosslinks and stabilizing replication forks." (PMID 40841483, 2026). "Furthermore, it is noteworthy that bi-allelic inheritance of mutations in BRIP1, as well as BRCA2 and PALB2, contributes to the rare disease of Fanconi anemia, with patients being prone to both hematological and solid cancer development." (PMID 40988318, 2025). "Except for the mosaic NONO mutation and homozygous DIS3L2, BLM, and BRCA2 alterations in syndromic patients (Perlman, Bloom, Fanconi anemia), all predisposing genetic changes occurred as heterozygous germline events." (PMID 40340749, 2025). "Similarly, in Fanconi anemia models harboring mutations in FA/BRCA pathway genes, including BRCA2, defective DNA repair has been shown to cause hyperactivation of the TGF-β pathway, resulting in tissue damage and fibrosis." (PMID 40723533, 2025). "We validated the association of USP44 with BRCA2, one of the proteins identified in our study—uncovering a previously unknown function of USP44 in the Fanconi anemia DNA repair pathway." (PMID 39767807, 2024). "Subsequently, BRCA2 interacts and activates components of the Fanconi anemia (FA) core complex." (PMID 39683594, 2024). "Our results identified a novel association between BRCA2 and USP44, and a previously unknown role for USP44 in the Fanconi anemia DNA repair pathway that may contribute to its role in cancer." (PMID 39767807, 2024). "However, RB1 (25%), as well as genes involved in the HRR (e.g., RAD51 in 18.8%) and Fanconi anemia (e.g., BRCA2 in 12.5%) pathways, were also recurrently hit by HetDels." (PMID 35406559, 2022). "FANCD2 (fanconi anemia complementation group D2), like BRCA2, may play an important role in the recombination DNA repair pathways." (PMID 36313179, 2022). "The R loop suppression activity of BRCA2 could be part of the coordinated roles between BRCA1 and BRCA2 in the HR pathway, or it could be part of the Fanconi anemia pathway to protect the replication fork." (PMID 36291894, 2022).
Fanconi anemia (continued). "However, given its strong associations with both Fanconi anaemia and homologous recombination repair, and the observation that it is embryonically lethal (like BRCA1 and BRCA2), this places C1ORF112 in the downstream stretch of the FA pathway." (PMID 33625522, 2021). "BRCA1 and BRCA2 (also present in the global downregulated network) are tumor suppressor genes belonging to the homologous recombination and Fanconi anemia pathways, involved in preserving chromosomal stability, regulating cell response to double-stranded DNA breaks and participating in DNA repair." (PMID 34660619, 2021). "In addition, Fanconi anemia patients with biallelic mutations in BRCA1, BRCA2 and PALB2 show an increased risk of hematological malignancies and solid tumors." (PMID 33923105, 2021). "The breast cancer susceptibility 2 (BRCA2) gene was identified in 1995 and has been shown to play an essential role in DNA double strand break (DSB) repair by homologous recombination (HR) and DNA crosslink repair by the Fanconi anemia (FA) pathway." (PMID 35052422, 2021). "Additionally, Su-Dhl-4 cells treated with entinostat or tazemetostat also showed downregulation of RAD51, RAD54L, BRCA2, and three Fanconi anemia genes (FANCA, FANCB, and FANCM)." (PMID 31829282, 2019). "BRCA1, BRCA2, and PALB2 were among the genes associated with the Fanconi anemia pathway." (PMID 30719229, 2019). "The gene panel used for the analyses of the DNA of 41 patients by massive sequencing detected the presence of numerous variants in genes coding for proteins involved in DNA repair such as ATM, ATR, BRCA1, BRCA2 and several genes of the FANC complex, mutated in Fanconi Anemia." (PMID 30995915, 2019). "Moreover, exons 14 and 15 coding region is also recognized by FANCD2 (Fanconi anemia group D2) protein, which binds to the BRCA2 protein between codons 2350 and 2545." (PMID 31191615, 2019). "This phenotype was present in cells defective for breast cancer susceptibility genes BRCA1 and BRCA2, or Fanconi Anemia genes FANCD2, or FANCA, but not in the wild type cells." (PMID 29355244, 2017). "This would explain the weak genotype to phenotype correlation with this variant as well as the observation that this variant has been found in trans with other pathogenic BRCA2 mutations, without causing Fanconi Anemia." (PMID 28591191, 2017). "Recent evidence indicates that R-loops might also be formed in human cells, for which DNA repair proteins such as BRCA1, BRCA2 and other Fanconi Anemia factors could play a kind of back-up system to remove then." (PMID 27035147, 2016). "Moreover, BRCA2 is also known as FANCD1, because some mutations in this gene predispose to a syndrome called Fanconi anemia, characterized by bone marrow failure and blood cancer." (PMID 25848704, 2015). "To date, however, there has been no report of a medulloblastoma associated with a deleterious BRCA2 germline mutation in a patient without Fanconi anemia." (PMID 26380221, 2015). "Previous studies have suggested MMC may perturb the Fanconi anemia pathway, in which BRCA2 plays a major role." (PMID 20174566, 2010). "It is unclear at this stage whether the remaining seven MMC responsive genes play a role in the Fanconi anemia pathway, and how they are functionally linked to BRCA1 and/or BRCA2." (PMID 20174566, 2010). "It is interesting that most of the Fanconi anaemia genes encode proteins that form a nuclear core complex with a function of monoubiquitination of FANCD2, but FANCD1 (BRCA2) and BRIP1/FANCJ function downstream of this and they both have a more defined role in DNA damage repair." (PMID 19127258, 2009).
Fanconi anemia (continued). "Relationships and critical interactions exist among BRCA1, BRCA2 and Fanconi anemia proteins." (PMID 17683622, 2007). "A recent study has suggested that there may be an additional mechanism that ensures the persistence of microaerophilic bacteria like C. acnes by invading epithelial cells, interfering with homologous repair and Fanconi anemia pathways through downregulating the expression of BRCA2." (PMID 39796699, 2024). "Monoallelic germline pathogenic variants (GPVs) in five Fanconi anemia (FA) genes (BRCA1/FANCS, BRCA2/FANCD1, PALB2/FANCN, BRIP1/FANCJ, and RAD51C/FANCO) confer an increased risk of breast (BC) and/or ovarian (OC) cancer, but the role of GPVs in 17 other FA genes remains unclear." (PMID 39149814, 2024). "In addition, whether other members in the Fanconi Anemia pathway, besides BRCA2, are involved in restricting R-loop levels at the bivalent regions is worth further exploration." (PMID 35715464, 2022). "Likewise, biallelic BRCA1, BRCA2, BRIP1, PALB2 and RAD51C mutations lead to Fanconi anemia." (PMID 36292468, 2022). "Although they mainly affect the BRCA1 and BRCA2 genes, they have been detected in other genes such as RAD51C hypermethylation (RAD51 paralog C), ATM (ataxia telangiectasia mutated serine-protein kinase gene), or ATR mutations, and mutations of the HR interacting Fanconi anemia gene." (PMID 34638899, 2021). "However, because the patient did not present with a phenotype of Fanconi’s Anemia these variants are likely to be in the same BRCA2 allele (i.e. in cis)." (PMID 29161300, 2017). "P/LP germline variants were recurrent in homologous recombination (n = 9; BRCA1, BRCA2, PALB2) and Fanconi anemia genes (n = 4)." (PMID 40072012, 2025). "The formation of R-loops promotes the accumulation of Fanconi anemia factors (FANCD2, FANCA, FANCM, and BRCA2) at fragile sites, and the DEAD-box RNA helicase DDX47 is recruited to interact with FANCD2 to resolve the R-loops." (PMID 40271193, 2025). "The Fanconi anemia (FA) repair pathway promotes the excision of ICLs using at least 22 FANC proteins, including FANCS/BRCA1 and FANCD1/BRCA2." (PMID 38714348, 2024). "This pathway involves multiple proteins, including BRCA1, BRCA2, proteins of the MRN complex, CtIP, RAD51, ATM, H2AX, PALB2, RPA, RAD52, and proteins of the Fanconi anemia pathway." (PMID 38236558, 2024). "BRCA2 and FANCA are key genes of the Fanconi anemia pathway, and their expression was also significantly lower in V30 than in the control mice." (PMID 38646488, 2024). "Approximately half of high-grade serous epithelial ovarian cancers incur alterations in genes of homologous recombination (BRCA1, BRCA2, RAD51C, Fanconi anemia genes), and the rest incur alterations in other DNA repair pathways at high frequencies." (PMID 37684587, 2023). "In our experiments, the most significant upregulated genes included FANCD2, a player in Fanconi anemia (FA), and several genes playing a role in the HR-mediated repair of double-strand breaks (DSBs) such as BARD1, BRCA2, RAD51 and DNA2." (PMID 36672885, 2023). "FANCG was shown to play an important role in the activation of the Fanconi anemia (FA) pathway with the localization of the nuclear FA complex (including FANCG), and it can also interact with FANCD1 (BRCA2)." (PMID 35488336, 2022). "This occurs in part via a Wnt/β‐catenin pathway acting in part through MYBL2, that enhances the expression of genes involved in homologous recombination and Fanconi anemia pathways, including BRCA1, BRCA2 and multiple FANC genes." (PMID 33660437, 2021). "The associations involving DNA double-strand break repair pathway and Fanconi anemia, in particular, were also evident when examining key individual genes, including BRCA1, BRCA2, FANCD2, FANCI, and RAD51." (PMID 31610796, 2019).